DNMT3B (DNA methyltransferase 3 beta)
Diseases named in the same sentence as DNMT3B in open-access papers (continued):
Sharing a sentence is not in itself a finding about the gene and the disease.
cancer (continued). "Godley and colleagues documented over 20 DNMT3B transcripts from various cancer cell lines and primary acute leukemia cells that were alternatively spliced at the 5' end of the gene." (PMID 25198254, 2014). "The DNMT3b silencing vector significantly inhibited DNMT3b expression in cancer cells by Western blotting and immunochemical staining analysis." (PMID 24625449, 2014). "A significant positive correlation was observed in the cancer specimen that stained positively for DNMT3b and IL-6." (PMID 24625449, 2014). "Nanaomycin A was found to selectively inhibit DNA (cytosine-5-)-methyltransferase (DNMT3B) and reactivate silenced tumor suppressor genes in human cancer cells." (PMID 24595456, 2014). "Previous studies have shown that a reduction of DNMT3B protein levels induces antiproliferative effects in cancer cells that were attributed to the demethylation and reactivation of tumor suppressor genes." (PMID 22563479, 2012). "In a variety of cancers, DNMT1, DNMT3a, and DNMT3b were reported to be highly expressed and associated with poor prognosis." (PMID 22768205, 2012). "DNMT3b is constitutively expressed by all mammalian cell types, but is frequently overexpressed in cancer." (PMID 22664488, 2012). "The de novo DNA methyltransferase 3B (DNMT3B) has been suggested to play an important role in the generation of cancer-specific methylation patterns." (PMID 22563479, 2012). "Based on these observations we developed a model to illustrate the potential function of DNMT3B in cancer development: In normal cells, CpG islands are generally unmethylated and the corresponding genes are actively transcribed." (PMID 22563479, 2012). "Our results suggest that DNMT3B is required for maintaining proliferation and for preventing apoptosis in cancer cell lines with a high level of endogenous DNMT3B." (PMID 22563479, 2012). "Our data indicate that the depletion of DNMT3B - while inhibiting proliferation and inducting apoptosis - does not induce any significant DNA methylation changes in established cancer cell lines." (PMID 22563479, 2012). "MicroRNA-29b has been shown to target and knock down expression of both DNMT3A and DNMT3B in cancer cells, with a consequent decrease in genome-wide methylation." (PMID 21712824, 2011). "DNMT3B depletion in human cancer cell lines reactivated methylation-silenced gene expression but did not induce global or juxtacentromeric satellite demethylation." (PMID 20838441, 2010). "The aberrant CpG methylation patterns in human cancer cells are inscribed by the de novo DNA cytosine-5 methyltransferases (DNMTs), DNMT3a and DNMT3b, and transmitted in the subsequent cell generations by the maintenance DNMT1." (PMID 21629434, 2010). "DNMT3b expression has also been found to be essential for cancer cell survival by inhibiting apoptosis of tumour cells but not normal cells." (PMID 18414412, 2008). "We next assessed the global changes in gene expression induced by siRNA of DNMT1 constructs or siRNA of DNMT3B constructs in hepetocellular carcinoma cell lines SMMC-7721." (PMID 27994704, 2008). "It is suspected that DNMT3b is at least partially responsible for the aberrant methylation observed in cancer cells and that it is required for the active suppression of genes." (PMID 17938735, 2007). "The genetic disruption of two DNMTs, DNMT1 and DNMT3b, in a cancer cell line induces demethylation of all known hypermethylated tumour-suppressor genes and remarkably slow growth." (PMID 16404435, 2006). "While the consequences of satellite 2 hypomethylation in ICF and cancer require much more study, it is already clear that the causes of satellite 2 hypomethylation in cancer and in ICF patients with DNMT3B-linked disease probably differ." (PMID 16722602, 2006). "DNMT1 and DNMT3b are known to catalyse DNA methylation in cancer cells; the mechanism by which DNA methylation represses gene expression is not fully understood, however, although histone deacetylation reportedly plays a key role." (PMID 15756280, 2005).
cancer (continued). "DNMT3B can promote the progression of multifarious malignant tumors." (PMID 41660264, 2025). "Moreover, DNMT3B targeting using genetic depletion or miR-29 mimics reduces cancer cell growth and survival in several tumor models, thereby confirming its oncogenic role." (PMID 40241199, 2025). "DNMT3B is an important DNA methyltransferase related with unfavorable outcomes for cancer patients." (PMID 41660264, 2025). "Our analysis identified three candidate genes with increased expression in cancer tissues, with elevated levels associated with poor survival across multiple cancer types: the 5-methylcytosine methyltransferases NSUN2 and DNMT3B and CBP20, an N7-methylguanosine binding protein." (PMID 40887503, 2025). "This occurs through the downregulation of DNA methyltransferases DNMT1, DNMT3A, and DNMT3B, and the upregulation of Methyl CpG Binding Domain Protein 2 (MBD2), a marker often associated with cancer due to its role in causing genomic instability and increasing mutation frequencies." (PMID 39829957, 2025). "Moreover, overexpression of DNMT1, DNMT3A, and DNMT3B at the mRNA level was observed in bladder, kidney, colon, and pancreas human cancers." (PMID 41226543, 2025). "Furthermore, in line with its suggested role in cancer cell stemness, DNMT3B targeting also strongly reduced MM cell clonogenic outgrowth, which is the ability of a single cell to grow out into a colony." (PMID 40241199, 2025). "Overexpression of DNMTs (e.g., DNMT1, DNMT3A and DNMT3B) could promote DNA hypermethylation, which was closely related to the prognosis in cancer patients (Weisenberger, Lakshminarasimhan & Liang, 2022)." (PMID 38766487, 2024). "This highlights DNMT3B as a potential target for cancer therapy." (PMID 39185313, 2024). "Many different DNMT3B splice isoforms have been reported to be aberrantly expressed in cancer." (PMID 38291337, 2024). "Thus, DNMT3B is likely involved in coordinating metabolic and epigenetic adaptations that enable cancer cells to sustain proliferation under diverse conditions." (PMID 39684755, 2024). "In conclusion, circRNAs by modulating DNMT3B activity have the potential to assume a progressively significant role in the epigenetic regulation governing the initiation and advancement of human cancer." (PMID 37705098, 2023). "Interestingly, most of these genes are linked with cancer processes (Pld1, Fam13c, Svbp, TMem192, Zc3h7a, RTP4, Naa30, Zgrf1, Slc33a1, Dnmt3b, Map6, Plin4, Eps8L2, Alg12, Capg and Tdp2)." (PMID 37700325, 2023). "Therefore, their findings emphasize DNMT3B significance in both gene expression and the development of human cancer." (PMID 37705098, 2023). "HDACs and DNMT3B act as transcriptional repressors for tumor suppressor genes, high mRNA levels of HDAC3 and DNMT3B are associated with poor prognosis in patients with different types of cancer." (PMID 36870998, 2023). "Consequently, the ncRNA/DNMT3B axis holds promise as a therapeutic target for the management of human cancer." (PMID 37705098, 2023). "Notably, DNMT3B, a de novo DNA methyltransferase, has been considered as an oncogene in cancer initiation and progression." (PMID 37072414, 2023). "Interestingly, colorectal HCT116 and pancreatic MIA PaCa-2 cancer cell lines displayed significantly elevated DNMT3B protein levels upon MG stress." (PMID 36998085, 2023). "Thus, a critical avenue for advancing cancer prevention and treatment is an inquiry into the interplay between DNMT3B and ncRNAs." (PMID 37705098, 2023). "Importantly, we have shown that these cells lose their migratory capacity upon DNMT3B knockdown thus illustrating the link between MG stress pro-cancer phenotype and altered DNA methylation machinery." (PMID 36998085, 2023).
cancer (continued). "Along with epigenetic modifiers that were previously implicated in cancer cell fitness, such as CHD1, CHD4, DNMT3B, ELP3, SUPT16H, SUV39H2; novel hits ASH2L, RBX1 and SSRP1 were discovered as essential genes for both U373 and T98G cells suggesting common regulatory role." (PMID 37974198, 2023). "Then, we sought to explore whether MG stress could up regulate DNMT3B level in other human cancer cell types that we stably depleted for GLO1 expression." (PMID 36998085, 2023). "DNMT3B has several target genes in cancer, including oncogenes and tumor suppressors." (PMID 36460706, 2022). "RASSF1A is a gene that can be regulated by DNMT3B via DNA methylation in cancer." (PMID 36460706, 2022). "We interrogate the DNMT3B levels and disease-free survival in cancer patients in TCGA data sets." (PMID 36460706, 2022). "In the genomic structural sense, we investigate common cis elements in downregulated genes by DNMT3B overexpression and in the functional sense, we evaluated the methylation and expression status of four cancer-related genes and the impact of DNMT3B in a key biological process in cancer." (PMID 36460706, 2022). "Each DNMT3B isoform has a cell-specific role in maintaining the optimal function of DNMTs in the tissue, and transcriptional deregulation could be a part of cancer development." (PMID 36012258, 2022). "Cancer cell lines are good study models for investigation of the heterogenous factors that contributed to a specific cancer type, nevertheless, with immortalized keratinocytes model (HaCaT) we trying to emulate the onset stage and a first-line event in cancer, DNMT3B up-regulation." (PMID 36460706, 2022). "In addition, OAS3 was positively correlated with four major DNA methyltransferases including DNMT1, DNMT2, DNMT3A, and DNMT3B in most cancer types." (PMID 35592250, 2022). "In addition, recent studies have identified many targets for DNMT3B, including tumor‐suppressor genes in cancer cells." (PMID 34133843, 2022). "Green tea polyphenols could inhibit DNMT3B mRNA expression and thus reduce tumors in different tissues or cancer cells." (PMID 35627221, 2022). "Interestingly, previous studies report delocalization of DNMT3B in cancer and link this phenomenon, at least partially, to oxidative stress and DNA repair mechanisms." (PMID 34439480, 2021). "In addition, we comparatively analyzed the m5C regulators’ expression levels in cancers and corresponding normal tissues and found out that DNMT3B was significantly overexpressed in thirty-three tumor or cancer tissues compared with adjacent normal tissues." (PMID 34325709, 2021). "Cancer-associated genes of the locus include ASXL1, DNMT3B, BCL2L1, TPX2, KIF3B and POFUT1." (PMID 34577783, 2021). "Global DNA hypomethylation in cancer and subsequent H3K27me3 hiBiv depletion may be sufficient for aberrant DNMT3B activity to promote hypermethylation at these regions." (PMID 32131813, 2020). "Among DNMT1, DNMT3A and DNMT3B, mutations in DNMT3A have been reported most frequently in cancer." (PMID 32751889, 2020). "One meta-analysis suggests that DNMT3B -283T/C and DNMT3B -579G/T may play a protective role against different types of cancers." (PMID 33369477, 2020). "Interestingly, BRAP expression was strongly correlated with DNMT1, DNMT2, DNMT3A, and DNMT3B expression in human pan-cancer, and UCS, TGCT, and SARC were exceptions." (PMID 33240929, 2020). "We observed that DNA methyltransferase genes such as DNMT1, DNMT3A, and DNMT3B were overrepresented in all cancer groups, with a significant difference between the SH and SL samples in both ADCs and SCCs, which prompted us to explore the genome for the methylation states." (PMID 33343623, 2020).
cancer (continued). "Indeed, Sp1 inhibition significantly attenuated TERT-mediated DNMT3B up-regulation, while its over-expression restored DNMT3B expression in TERT-depleted cancer cells." (PMID 31911897, 2019). "Thereinto, DNMT3B is upregulated in 9 cancer types, and its higher expression showed a correlation with overall survival in 5 cancer types and it might contribute to the specific DNA methylation disorder." (PMID 31828117, 2019). "We then choose the overlap genes which harbor differential methylation and expression; meanwhile, many of these genes are involved in different functional annotation that depends on the tissue types, suggesting that DNA methylation at different loci happens through DNMT3B in different cancers." (PMID 31828117, 2019). "The results of this study could provide therapeutic strategies for the HCC patients expressing cancer stemness properties such as DNMT3b/OCT4 expression and/or sorafenib resistance." (PMID 31771617, 2019). "DNMT3B is the major de novo DNA methyltransferase expressed and active during the early stages of embryonic development, and is impaired in human diseases with chromosomal and genomic instabilities, including inherited diseases and cancer." (PMID 31370354, 2019). "Additionally, cancer cell lines harboring DNMT3B gene amplification are less sensitive to the decrease in cell viability caused by HMAs." (PMID 31331399, 2019). "In contrast, a notable fraction of human cancers show deregulated DNMT3B expression." (PMID 30468428, 2018). "In cancer tissues, DNMT3B is expressed more frequently compared to DNMT1 and DNMT3A." (PMID 29796115, 2018). "CGI shores have previously been shown to be hypermethylated in cancers and we found several orthologous human tumor suppressor genes or biomarkers that gained methylation at promoter-proximal CGIs and shores when Dnmt3b was overexpressed in mouse tissues." (PMID 30468428, 2018). "DNMT3B is overexpressed and is involved in the methylation of genes in cancers." (PMID 29796115, 2018). "In addition to having a methyl-transferase activity, DNMT3B also acts as an accessory protein in complex with DNMT3A contributing to aberrant methylation in cancer." (PMID 29928480, 2018). "Our genome-wide data combined with ultra-deep locus-specific bisulfite sequencing suggest a distributive activity of ectopically expressed Dnmt3b that leads to discordant CpG island hypermethylation and provides new insights for interpreting the cancer methylome." (PMID 30468428, 2018). "Comparison of features between the ectopic Dnmt3b expression and human cancers." (PMID 30468428, 2018). "Dnmt3b overexpression in human cancer types and an ectopic mouse model." (PMID 30468428, 2018). "This study was an attempt to compare CPUK02 with 5-AZA as DNMT inhibitor agent and evaluate whether it can induce its anti-cancer effects via altering the level of DNMT3b mRNA, MGMT and SFRP2 methylation pattern in HCT 116 cell line." (PMID 28090275, 2017). "Ostleret al. suggested that the abnormal DNA methylation patterns which are present in nearly all cancer cells may be regulated by enzymatically inactive DNMT3B proteins." (PMID 28160561, 2017). "We compared mRNA levels of DNMT1, DNMT3A, total DNMT3B, and DNMT3B variants in cancer tissue with those in matched adjacent normal tissue." (PMID 28160561, 2017). "DNMT levels—especially those of DNMT3A and DNMT3B—are often increased in various cancer tissues and cell lines, which may partly account for the hypermethylation of CpG-rich regions in tumor suppressor gene promoters in various malignancies." (PMID 28616099, 2017). "In addition, multiple isoforms of DNMT3B were also significantly overexpressed in these types of cancers, including catalytically inactive DNMT3B3." (PMID 27121154, 2016). "In addition, we confirmed the aberrant expression of DNMT3B isoforms in various cancers, using publically available data sets." (PMID 27121154, 2016).
cancer (continued). "We next examined whether KDM1A knockdown might affect levels of DNMT1 and/or DNMT3B transcripts in cancer cells." (PMID 27449289, 2016). "However, there are recent reports that DNMT1 works together with DNMT3b in silencing genes in human cancer cells." (PMID 27317771, 2016). "In addition, to provide further evidence on DNMT3B role in silencing germ line genes, these findings are of particular interest in the context of other human disease, like cancer." (PMID 26161907, 2015). "A number of studies showed that DNMT3B was up-regulated in several human cancers, demonstrating that DNMT3B may play an important role in tumorigenesis by contributing to the generation of aberrant DNA methylation." (PMID 25433949, 2015). "DNMT3b expression was evaluated in 104 cancer tissues by immunohistochemistry method." (PMID 26262893, 2015). "Exposure of various cancer cell lines to 5-aza-2-deoxycytidine causes radiosensitization accompanied by inhibition and downregulation of DNMT1 and DNMT317, 56; therefore, further research into the development of specific inhibitors of DNMT3B is required." (PMID 26667181, 2015). "Interestingly, two recent studies showed that depleting either DNMT1 or DNMT3B in cancer cells protects them from gene misregulation and cell cycle arrest induced by a DAC treatment, hence supporting our present findings." (PMID 25948775, 2015). "We focused on the epigenetic regulator DNMT3B, which was identified as a candidate target gene in the cluster of DNA repair/epigenetic factors/transcriptional factors, because it is overexpressed frequently in cancers." (PMID 26667181, 2015). "The mechanism of the association between DNMT3B 149 C→T polymorphism and the risk of cancer is not clearly understood." (PMID 24850984, 2014). "One study with prostate cancers demonstrated that the activity of DNMT1, DNMT3a, and DNMT3b are twofold to threefold higher in cancer cell lines and cancer tissues, as compared with a benign prostate epithelium cell line and benign prostatic hyperplasia tissues." (PMID 24822169, 2014). "As the results of different studies have shown, there is no consensus regarding the association between DNMT3B genotypes and the risk of cancer." (PMID 24850984, 2014). "DNMT3B has been shown to play a crucial role in incorporating de novo hypermethylation of promoter CpG islands, a possible mechanism for tumor suppressor gene inactivation within human cancer cells." (PMID 24822169, 2014). "DNMT3B mutations in cancer have not currently been found but aberrant splicing of DNMT3B frequently gives rise to cancer-specific isoforms of the enzyme." (PMID 23341493, 2013). "The mechanism(s) by which cancer cells acquire alteration in DNA methylation is unknown but aberrant transcription of the DNMT3B gene is frequent." (PMID 23251566, 2012). "To determine the mRNA expression of DNMT3B in various human tissues and cancers, we analyzed the expression profiles in the Array Northern database, which is based on hybridization of RNA to the Affymetrix HGU133Plus2.0 array integrating internally and externally generated data." (PMID 22563479, 2012). "However, only few studies have investigated the specific role of DNMT3B in the establishment and maintenance of aberrant hypermethylation patterns in cancer cells." (PMID 22563479, 2012). "The co-ocurrence of DNMT3B overexpression and promoter hypermethylation observed in many human cancers suggested that DNMT3B-mediated de novo methylation might be functionally relevant for tumor development." (PMID 22563479, 2012). "As DNMT3B is mediating de novo DNA methylation and thus epigenetically inactivates tumour suppressor genes in cancer, these observations connect blocked differentiation through CEBPA suppression with deregulated methylation because of the suppressed miR-29b activity." (PMID 20628397, 2010). "In parallel, targeting DNMT3b might be a potential approach for cancer therapy." (PMID 41596471, 2026).